SKIL (SKI like proto-oncogene)
Description:
May have regulatory role in cell division or differentiation in response to extracellular signals.
Synonyms: SNO; SnoN; SnoA; SnoI
Tractability: PROTAC: UniProt records ubiquitination sites on it; ubiquitination databases record sites on it.
Gene: Protein-coding gene on chromosome 3 (170,357,287 to 170,396,835, forward strand). Ensembl gene ENSG00000136603.
Subcellular location (Human Protein Atlas): Nucleoplasm; Cytosol
Pathways (Reactome):
Signal Transduction: Downregulation of SMAD2/3:SMAD4 transcriptional activity
Gene Ontology:
Molecular function: DNA-binding transcription repressor activity, RNA polymerase II-specific; protein binding; RNA polymerase II cis-regulatory region sequence-specific DNA binding; DNA-binding transcription factor activity, RNA polymerase II-specific; SMAD binding; chromatin binding
Biological process: negative regulation of BMP signaling pathway; negative regulation of transcription by RNA polymerase II; negative regulation of transforming growth factor beta receptor signaling pathway; muscle structure development; positive regulation of axonogenesis; regulation of neurogenesis; response to cytokine; spermatogenesis
Cellular component: nucleoplasm; protein-containing complex; cytoplasm; nucleus; transcription regulator complex; acrosomal vesicle; PML body
Genetic constraint (gnomAD): Loss-of-function variants: 9 observed, 29.93 expected, observed/expected ratio (o/e) 0.3, 90% interval 0.18 to 0.52. The upper end of that interval is the gene's LOEUF score, 0.52, which puts it in group 2 of 6, group 1 being the genes least tolerant of losing a copy. Missense variants: 423 observed, 476.75 expected, observed/expected ratio (o/e) 0.89, 90% interval 0.82 to 0.96. Synonymous variants: 191 observed, 178.44 expected, observed/expected ratio (o/e) 1.07, 90% interval 0.95 to 1.21.
Homologues: Orthologues: chimpanzee SKIL (99% identical), dog SKIL (92% identical), macaque SKIL (92% identical), rabbit SKIL (92% identical), guinea pig SKIL (90% identical), pig SKIL (90% identical), rat Skil (89% identical), mouse Skil (88% identical), tropical clawed frog skil (65% identical), zebrafish skila (48% identical), zebrafish skilb (38% identical). Paralogues in human: SKI (38% identical), SKOR1 (19% identical), SKOR2 (19% identical).